ZNF474 (zinc finger protein 474)
Synonyms: 4933409D10Rik; FLJ32921
Tractability: Antibody: the Human Protein Atlas places it where antibodies can reach. PROTAC: ubiquitination databases record sites on it.
Gene: Protein-coding gene on chromosome 5 (122,129,546 to 122,182,658, forward strand). Ensembl gene ENSG00000164185.
Subcellular location (Human Protein Atlas): Nuclear membrane; Nucleoplasm; Plasma membrane
Gene Ontology:
Molecular function: protein binding
Genetic constraint (gnomAD): Loss-of-function variants: 0 observed, 0.21 expected, observed/expected ratio (o/e) 0, 90% interval 0 to 1.88. That is too few expected variants to judge how well the gene tolerates losing a copy. Missense variants: 511 observed, 457.4 expected, observed/expected ratio (o/e) 1.12, 90% interval 1.04 to 1.2. Synonymous variants: 192 observed, 170.85 expected, observed/expected ratio (o/e) 1.12, 90% interval 1 to 1.27.
Homologues: Orthologues: macaque ZNF474 (92% identical), mouse Zfp474 (66% identical), rat Zfp474 (63% identical), Caenorhabditis elegans znf-474 (16% identical), Drosophila melanogaster CG42675 (11% identical), Drosophila melanogaster CG30460 (10% identical). Paralogues in human: ZNF475 (13% identical), ZC2HC1A (11% identical), ZC2HC1B (9% identical).
Diseases named in the same sentence as ZNF474 in open-access papers:
ZNF474 is named in the same sentence as 1 disease in open-access papers, as found by Europe PMC text mining. Sharing a sentence is not in itself a finding about the gene and the disease. The quoted sentences say what the papers report.
glioma (1 paper, 2024). A benign or malignant brain and spinal cord tumor that arises from glial cells (astrocytes, oligodendrocytes, ependymal cells). "Risk scores were assigned to each glioma patient based on a specific formula: risk score = HOXA20.158262352253815 + CHI3L10.163539741852195 + POSTN0.122461088150864 + OASL0.160406690819272 + ZNF474 × 0.333919193479214." (PMID 38473752, 2024). "We identified five critical genes (HOXA2, CHI3L1, POSTN, OASL, and ZNF474) with substantial roles in the glioma context." (PMID 38473752, 2024).